LINC00668 (long independently transcribed non-coding RNA 668)
Gene: Long non-coding RNA gene on chromosome 18 (6,919,496 to 6,930,019, reverse strand). Ensembl gene ENSG00000265933.
Diseases named in the same sentence as LINC00668 in open-access papers:
LINC00668 is named in the same sentence as 19 diseases in open-access papers, as found by Europe PMC text mining. Sharing a sentence is not in itself a finding about the gene and the disease. The quoted sentences say what the papers report.
breast carcinoma (5 papers, 2019 to 2025). "Patients with breast cancer and high expression of Linc00668 exhibited an increased risk of lymphatic metastases." (PMID 41181715, 2025). "In this study, we observed that higher levels of Linc00668 were associated with lymphatic metastasis in breast cancer patients." (PMID 32117742, 2020). "In conclusion, we identified the elevated expression of Linc00668 in breast cancer and which was associated with cancer metastasis." (PMID 32117742, 2020). "Recent studies suggest Linc00668 as a marker in breast cancer risk prediction and facilitating tumor growth." (PMID 32117742, 2020). "We further observed that higher levels of Linc00668 were associated with lymphatic metastasis in breast cancer patients." (PMID 32117742, 2020). "The exact cause of elevated expression of Linc00668 in breast cancer remained to be identified." (PMID 32117742, 2020). "Kaplan-Meier survival analysis showed that breast cancer patients with high expression of Linc00668 exhibited a shorter disease free survival compared with patients whose tumors expressed lower levels of Linc00668." (PMID 32117742, 2020). "LINC00668 promoted tumorigenesis and progression and indicated poor prognosis in not only breast cancer but also other cancers, such as colorectal cancer, hepatocellular carcinoma and non-small-cell lung cancer." (PMID 32867770, 2020). "As cytotoxic treatment has often been reported to enrich BCSCs, as expected, Linc00668 expression was elevated in Dox resistant breast cancer cells and forced expression of Linc00668 promoted the development of the resistance to Dox." (PMID 32117742, 2020). "We demonstrated that forced expression of Linc00668 enhanced, whereas depletion of Linc00668 diminished invasion and self-renewal of breast cancer cells as well as resistance to doxorubicin (Dox)." (PMID 32117742, 2020). "A higher Linc00668 expression level was observed in the breast cancer tissue samples compared to the benign breast tissue samples." (PMID 32117742, 2020). "To assess the role of Linc00668 in the development of breast cancer, we first analyzed expression of Linc00668 in 113 normal breast tissue samples and 1,091 breast cancer samples from the TCGA datasets." (PMID 32117742, 2020). "Herein, we observed that the expression of Linc00668 was increased in breast cancer compared to normal tissue." (PMID 32117742, 2020). "Collectively, these results demonstrated that Linc00668 enhanced stem cell-like characteristics in breast cancer cells." (PMID 32117742, 2020). "Herein, we reported the elevated expression of Linc00668 in breast cancer tissues compared to benign breast tissues and which was associated with a higher metastatic capacity." (PMID 32117742, 2020). "In both basal and luminal breast cancer cells, linc00668 acts by binding to SND1, which recognizes conserved motifs from the SMAD2/3/4 promoters and induces the expression of its target genes, which are well known to induce the TGF-β signaling pathway, essential for maintaining stemness." (PMID 41181715, 2025). "Hence, we further determined if Linc00668 regulated the sensitivity to doxorubicin in breast cancer cells." (PMID 32117742, 2020). "Thus, Linc00668 plays an important role in breast cancer progression including the development of chemotherapeutic resistance." (PMID 32117742, 2020). "As higher Linc00668 levels have been suggested to be involved in the regulation of breast cancer metastasis, we further determined if Linc00668 could regulated breast cancer cell migration and invasion." (PMID 32117742, 2020). "However, the multiple role of Linc00668 in breast cancer remains to be further studied." (PMID 32117742, 2020). "Hence, it may be suggested that Linc00668 is functionally involved in breast cancer development and progression." (PMID 32117742, 2020). "Given this, Linc00668 may serve as a candidate target for BCSCs-based therapy in breast cancer." (PMID 32117742, 2020).
breast carcinoma (continued). "Linc00668 depletion led to reduced expression of the downstream target of SND1 and further attenuated the self-renewal capacity of breast cancer cells." (PMID 32117742, 2020). "As it was suggested above that SND1 mediated Linc00668 function in breast cancer cells, we also examined the function of SND1 in breast cancer cells." (PMID 32117742, 2020). "We also examined the expression of Linc00668 in an array of mammary epithelial cell lines, including 2 non-transformed cell lines (HMEC hTERT, MCF-10A) and 6 breast cancer cell lines (T47D, MCF-7, SUM149, MDA-MB-231, HS578t, SUM159) by qRT-PCR." (PMID 32117742, 2020).
gastric cancer (4 papers, 2016 to 2022). A primary or metastatic malignant neoplasm involving the stomach. "E2F1 and STAT3 have been reported to promote the transcription of Linc00668, respectively, in gastric cancer and in lung cancer." (PMID 32117742, 2020). "It has also been reported that Linc00668, associating with the PRC2 complex, epigenetically silenced the cyclin-dependent protein kinase inhibitors (CKIs) and promoted cell proliferation in gastric cancer." (PMID 32117742, 2020). "To explore the mechanism of high expression of LINC00668, we examined the LINC00668 expression levels in gastric cancer cell lines." (PMID 27036039, 2016). "In addition, LINC00668 was a direct transcriptional target of E2F1, and LINC00668 could regulate gastric cancer cell proliferation both in vitro and in vivo." (PMID 27036039, 2016). "Therefore, we hypothesized that LINC00668 may play a distinct role in the cell cycle of gastric cancer." (PMID 27036039, 2016). "We further demonstrated that LINC00668 was associated with PRC2 and that this association was required for epigenetic repression of cyclin-dependent protein kinase inhibitors (CKIs), including p15, p16, p21, p27 and p57, thus contributing to the regulation of the gastric cancer cell cycle." (PMID 27036039, 2016). "On the other hand, we have observed the upregulation of genes that are involved in the proliferation, migration, and invasion of cancer cells in colorectal and gastric cancer (ANGPTL4, S100A8, LINC00668)." (PMID 35625760, 2022). "Moreover, we also found that LINC00668 plays a key role in the gastric cancer cell cycle by epigenetically silencing CDK inhibitors by binding to PRC2, which could in part account for LINC00668-mediated cell growth regulation." (PMID 27036039, 2016). "Our results suggest that E2F1-activated LINC00668, as a cell cycle regulator, enriches the mechanistic link between lncRNA and the E2F1-mediated cell cycle regulation pathway and may serve as a candidate prognostic biomarker and target for new therapies in human gastric cancer." (PMID 27036039, 2016).
lung squamous cell carcinoma (1 paper, 2019). "In our study, we found that the expression of LINC00668 is associated with A2ML1 and DNAJC12; of which A2ML1 has been shown to be closely related to the treatment of lung squamous cell carcinoma and can be used as a potential prognostic biomarker." (PMID 31850229, 2019).
rectal adenocarcinoma (1 paper, 2024). "LINC00668 is upregulated in microsatellite-stable colorectal and rectal adenocarcinoma with low microsatellite instability (respectively)." (PMID 38540157, 2024). "LINC00668 gene expression varies in rectal adenocarcinoma between subtypes with high and low microsatellite instability." (PMID 38540157, 2024).
thrombosis (1 paper, 2023). "Targeting LINC00668 can serve as a novel molecular treatment strategy to treat IBD‐related thrombosis." (PMID 37590310, 2023).
cancer (8 papers, 2019 to 2024). A tumor composed of atypical neoplastic, often pleomorphic cells that invade other tissues. "The potential for participation in cancer-associated processes decreases in a set of LINC00667, LINC00668 > LINC00470 > LINC01926, LINC01544, LINC01909, depending on the number of functional terms." (PMID 38540157, 2024). "According to previous study, it has been proved that LINC00668 is an oncogene in several cancers such as non-small-cell lung cancer and gastric cancer." (PMID 32249890, 2020). "Consistently qRT-PCR analyses of collected breast specimens of normal (N = 19) and tumorous (N = 54) tissue samples again revealed that Linc00668 expression was higher in 72.2% (39 of 54) of the cancer tissues compared to average of the normal tissues." (PMID 32117742, 2020). "It has been reported lncRNA LINC00668 serves as an oncogene in several cancers." (PMID 32249890, 2020). "Linc00668 also functioned as a ceRNA to promote tumor progression in several types of cancer." (PMID 32117742, 2020). "Furthermore, LINC00668 expression was found strikingly elevated in carcinoma cell lines (HepG2, SNU-387, MHCC-97H, Huh7) compared with normal liver cell line THLE-3." (PMID 32249890, 2020). "The more cancer-specific lincRNAs are LINC00470, LINC00668, LINC00907, LINC01254, LINC01415, LINC01478, and LINC01539." (PMID 38540157, 2024). "The expression of Linc00668 was significantly higher in the cancer cell lines compared to the non-transformed cell lines." (PMID 32117742, 2020).
tumor (6 papers, 2016 to 2024). "LINC00668 expression was significantly up-regulated in LUSC patients and high expression level of LINC00668 was associated with advanced tumor-node-metastasis (TMN) stage." (PMID 35477186, 2022). "After qRT-PCR analysis, we verified that LINC00668 did present a prominent up-regulation in HCC tumor tissues." (PMID 32249890, 2020). "Then qRT-PCR analysis also proved tumor tissues at advanced stages of HCC demonstrated a significantly higher expression of LINC00668 than those at early stages of HCC." (PMID 32249890, 2020). "Likewise, for LINC00668 and its co-expressed mRNA, with respect to tumor grade, expression levels were also higher with G3 disease than with G1, with statistical differences noted except for with LINC00668." (PMID 34532296, 2021). "Furthermore, LINC00668 was found prominently elevated in tumor tissue samples and cancerous cell lines." (PMID 32249890, 2020). "We found that the expression of RP11-334A14.8, RP4-738P11.4, TRBV6-6, LINC00668, and LINC00941 was higher in the relapsed tumor group than in the primary tumor group." (PMID 34532296, 2021). "According to the bar graph, we found that RP11-334A14.8, RP4-738P11.4, TRBV6-6, LINC00668, and LINC00941 expression levels were higher in the relapsed tumor group than in the primary tumor group." (PMID 34532296, 2021).
LINC00668 also shares sentences with these, for which no sentence is quoted: hepatic carcinoma (2 papers); laryngeal squamous cell carcinoma (2); lung carcinoma (2); acute myeloid leukemia (1); colorectal cancer (1); liver cancer (1); metastasis (1); non-small cell lung carcinoma (1); oral squamous cell carcinoma (1); pancreatic tumor (1); testicular germ cell tumor (1); thyroid cancer (1).